IL6 (interleukin 6)
Diseases named in the same sentence as IL6 in open-access papers (continued):
Sharing a sentence is not in itself a finding about the gene and the disease.
periodontitis (continued). "In periodontitis, microbial pathogens increase inflammatory infiltrate, that is, T-cells, B-cells, macrophages, and neutrophils with concomitant increase in inflammatory cytokines like IL-1, IL-11, IL-6, TNF-β, TNF-α, TGF-β, kinins, and thrombin." (PMID 29670909, 2018). "IL-6 is also known to play major roles in the pathogenesis of periodontitis." (PMID 30306207, 2018). "Moreover, a report on human gingival fibroblasts suggests that quercitrin increases the production of the extracellular matrix (ECM) and downregulates interleukin-6 (IL-6) mRNA and ROS levels, which contribute to the development of periodontitis." (PMID 29597317, 2018). "The association between IL-6 and periodontitis is not clear, due to the pro- and antiinflammatory actions of this interleukin." (PMID 29680852, 2018). "Also, when compared to healthy patients, subjects with gingivitis or periodontitis produce high levels of inflammatory mediators, such as IL-6 and TNF-α." (PMID 29740515, 2018). "Likewise, it has been seen that the IL-6 levels decrease after periodontal treatment in patients with periodontitis." (PMID 28809379, 2017). "Increased levels of IL-6 have been detected in the crevicular fluid of active sites compared with healthy sites of patients with refractory periodontitis and exposure to lipopolysaccharide from the P. gingivalis induces elevated levels of IL-6 and TNF-α in primary gingival mouse cell lines." (PMID 28632755, 2017). "AD patients with periodontitis have higher levels of serum IL-6 and TNF-α than uninfected controls." (PMID 28284226, 2017). "Gingival tissues of chronic periodontitis patients exhibit significantly higher levels of pro-inflammatory cytokines IL-1β, IL-6, IL-8, and TNFα than those of periodontally healthy subjects, hence it is possible that periodontal pathogen OMVs are contributing to this response." (PMID 28890719, 2017). "Although pro-inflammatory cytokines such as the interleukin-6 (IL-6) and IL-1β are regarded as osteolytic factors in periodontitis, there are reports suggesting that IL-6 and IL-1β also may drive osteogenic differentiation of PDL cells." (PMID 28597116, 2017). "Therefore, taking into account the important role of the gingipains secreted by P. gingivalis in the pathogenesis of periodontitis, here we studied their contribution to regulation of the IL-6-Th17 axis." (PMID 28497028, 2017). "The analysis in the present study shows that after NSPT, genetic susceptibility to chronic periodontitis in the IL-6 and IL-10 genes did not affect the periodontal treatment outcome." (PMID 28624837, 2017). "Thus, blocking of IL-6 signaling should be also considered as a potential strategy to treat periodontitis fueled by the inflammatory reactions propagated by periodontal pathogens." (PMID 28497028, 2017). "In a subset of patients with severe periodontitis, locally produced proinflammatory mediators—such as IL-1β, IL-6, and TNF-α—can enter systemic circulation and induce an acute-phase response in the liver that is characterized by an increased level of C-reactive protein (CRP)." (PMID 28243243, 2017). "Although abundant evidence does support an association between IL-6 and IL-10 genes polymorphisms with susceptibility to chronic periodontitis, we observed that NSPT was not influenced by the susceptible genotypes." (PMID 28624837, 2017). "Due to the crucial role of IL-6 in skewing lymphocytes toward Th17 phenotype, blocking of IL-6 function may become an attractive target for treatment of chronic inflammatory disease such as periodontitis." (PMID 28497028, 2017). "Since inactivation of gingipains accelerates the skewing of T cells toward Th17 cells, which are detrimental in periodontitis, IL-6 signaling may serve as an attractive target for treatment of the disease." (PMID 28497028, 2017). "Furthermore, a ligature-induced periodontitis rat model, increased lipid peroxidation and IL-6 expression was observed in aortic wall." (PMID 27386384, 2016).
periodontitis (continued). "It was reported that IL-6 induces osteoclastogenesis and alveolar bone resorption in periodontitis." (PMID 27834922, 2016). "IL6 is known to exert an important effect in the pathogenesis of periodontitis." (PMID 28050060, 2016). "In addition, IL-6 levels are also higher in the diseased gingiva of patients with periodontitis than in the gingiva of periodontally healthy subjects." (PMID 26859747, 2016). "Besides periodontitis, IL-6, IL-8, and CCL-5 as major proinflammatory mediators they also play critical roles in many inflammation-related diseases, including osteoarthritis and Parkinson’s disease." (PMID 27529418, 2016). "Serum IL-6 and C-reactive protein levels are high in people with periodontitis." (PMID 27115749, 2016). "In addition, proinflammatory cytokines significantly increased with the severity of periodontitis, and stimulated IL-6 was found to be an effective marker for predicting the periodontitis treatment outcome." (PMID 25884025, 2015). "Finally, our diverse analyses allowed us to provide potential thresholds to discriminate periodontitis (i.e., IL-1ß: 24–28 pg/mL; IL-6: 5.11–5.5 pg/mL; MIP-1α: 3.28–5 pg/mL, and MMP-8: 140–165.9 ng/mL)." (PMID 26347856, 2015). "Thus, the IL-6 difference is an effective marker for predicting the periodontitis treatment outcome." (PMID 25884025, 2015). "Salivary IL-1β and IL-6 significantly increased with the severity of periodontitis." (PMID 25884025, 2015). "However, using a threshold value of = 5.5 pg/mL, showed a significant increase in positive responses in the periodontitis patients with a highly significant RR = 4.1703 for elevated salivary IL-6 levels commensurate with periodontitis." (PMID 26347856, 2015). "Sites from refractory patient with periodontitis produced significantly more IL-6." (PMID 25648415, 2015). "Because bone resorption in periodontitis is induced by inflammatory cytokines IL-1, IL-6, and TNF-α29, the suppression of these inflammatory cytokines may be the key to successful treatment of periodontitis." (PMID 26561427, 2015). "In our study, a further interesting finding is the possible involvement of C. pneumoniae in the local chronic inflammation, as suggested by the increased levels of IL-1β and IL-6 detected in the gingival crevicular fluid of the patient with chronic periodontitis." (PMID 26636048, 2015). "Additionally, little is known about the effects of TCZ therapy on soluble receptors for IL‐6, acute‐phase proteins, and immunity that is mediated by macrophages, T cells, and B cells in patients with RA and periodontitis." (PMID 29744142, 2015). "Interleukin‐6 (IL‐6) and tumor necrosis factor‐alpha (TNF‐α) are pro‐inflammatory cytokines that regulate immune response and bone metabolism and have been suggested as one of the most potent cytokines that were associated with periodontitis and RA." (PMID 29744142, 2015). "Individuals with CPD in advanced stages, severe periodontitis, or PDag had significant IL-6 levels." (PMID 26339136, 2015). "Similarly, a significantly elevated concentration of salivary IL-6 was found in the periodontitis group (22.8 ± 3.7 pg/mL) compared to both the gingivitis (6.3 ± 2.7) and healthy (3.7 ± 0.5) subjects." (PMID 26347856, 2015). "Analysis of bisulfite genomic sequences has revealed that a total of 19 CpG motifs were identified from -1200 bp to +27 bp in IL-6 promoter region, and that the methylation levels of the CpG motif at -74 bp were lower in patients with chronic periodontitis (CP) and RA than in healthy controls." (PMID 25657893, 2015). "In mice with induced periodontitis we observed significantly increased levels of IL-6 which may be consistent with the observed increase in fetal weight." (PMID 25806806, 2015). "IL-6 is a multifunctional pro-inflammatory cytokine that plays a significant role in inflammation and also stimulates osteoclastogenesis and bone destruction in chronic inflammatory diseases such as periodontitis." (PMID 25226300, 2014).
periodontitis (continued). "We suppose that the higher median detected in the healthy group as compared to periodontitis patients group after stimulation of their lymphocytes by P. intermedia may be explained by the anti-inflammatory properties of IL-6." (PMID 25530681, 2014). "Periodontitis induced at the end of pregnancy resulted in increased production of IL-6, while the levels of PGE2 and IPB (induction factor of bactericidal permeability) increased only in groups that received ligature before pregnancy or in the 3rd month of pregnancy." (PMID 25688342, 2014). "In contrast, there are 3 reports of significantly elevated salivary IL-6 levels in periodontitis." (PMID 24944840, 2014). "Interestingly, IL-6 expression was found to be higher at sites of periodontal inflammation and closely related to clinical severity of periodontitis." (PMID 24877093, 2014). "Results showed increased levels of salivary IL-6 in periodontitis patients." (PMID 25548674, 2014). "In addition, T cells extracted from periodontitis patient expressed more IL-6 compared to T-cell from healthy controls." (PMID 24151615, 2013). "In a meta-analysis of cytokine gene polymorphisms of 53 studies, the IL-6 -174 polymorphism did not exhibit any association with chronic periodontitis (CP)." (PMID 23046796, 2012). "In the current study, IL-6 did not exhibit an association with periodontitis, in contrast to studies on Caucasians and Brazilians." (PMID 23046796, 2012). "Moreover, treatment of periodontitis is followed by a decrease in systemic markers of inflammation including IL-6, an effect mimicked in vitro by simvastatin in epithelial cells." (PMID 22203908, 2011). "In fact, case-control and intervention studies have clearly demonstrated that high-sensitivity C-reactive protein (hs-CRP) and interleukin (IL)-6 protein levels are higher in cases of periodontitis and that successful treatment of periodontitis decreases the levels of both mediators." (PMID 21625524, 2011). "The elevated levels of CRP and IL-6 in periodontitis patients may occur when bacteria and bacterial products, such as lipopolysaccharide (LPS), as well as locally produced pro-inflammatory cytokines enter the circulation." (PMID 20407653, 2009). "The present study was undertaken to examine whether serum levels of CRP and IL-6 are increased in periodontitis, and to determine the relationship of their elevated levels to the severity of periodontal disease." (PMID 20407653, 2009). "Anticytokine therapy for periodontal diseases especially targets proinflammatory cytokines, that is, TNF-α, IL-1, and IL-6, because these are essential for the initiation of the inflammatory immune reaction and are produced for prolonged periods in periodontitis." (PMID 20407652, 2009). "Recent evidence indicates that salivary analytes, including IL-6, exhibit measurable intra- and inter-day variability depending on daily activities such as eating or toothbrushing, yet remain reliable biomarkers for periodontitis detection, with IL-6 showing the highest measurement stability." (PMID 41007333, 2025). "An increased risk of developing periodontitis is associated with genetic polymorphisms of IL1A, IL1B, IL6, and TNFA genes and MMP-9 (−1562C/T), ANRIL rs1333048, rs1333042, rs2891168, and rs496892 polymorphisms might have impact on susceptibility to periodontitis, especially in Caucasian individuals." (PMID 41300760, 2025). "Its ability to down-regulate cytokines such as IL-1β, TNF-α, and IL-6, its interaction with IL-17 signaling, and its role in controlling osteoclast differentiation and alveolar bone resorption highlight its broader relevance in the pathogenesis of periodontitis." (PMID 41289041, 2025). "Future studies should focus on understanding how carriers of these specific HLA-DRB1 alleles may exhibit increased production of pro-inflammatory cytokines, including TNF-α, IL-1β, and IL-6, all of which are central to the tissue destruction seen in periodontitis." (PMID 40283738, 2025).
periodontitis (continued). "A cross-sectional study revealed increased serum levels of TNF-α and IL-6 in patients with cognitive impairment and periodontitis, which suggested that the presence of systemic inflammation in periodontitis patients may affect the progression of neurodegenerative diseases." (PMID 40933993, 2025). "To investigate whether FMT can improve intestinal barrier function and reduce inflammation in periodontitis mice, we further analyzed the colonic expression of tight junction proteins, inflammatory cytokines (IL-6, TNF-α), and MUC2 after different treatment conditions." (PMID 41040884, 2025). "In vivo, the exclusive reliance on a rat periodontitis model lacks representativeness, and the restricted focus on two inflammation-associated cytokines (TNF-α and IL-1β) overlooks other critical mediators (e.g. IL-6) and bone formation markers (e.g. BMP-2, OCN)." (PMID 40958806, 2025). "Furthermore, resveratrol decreased TNF-α, IL-1, and IL-6 levels in rats with periodontitis." (PMID 39456522, 2024). "Furthermore, in an in vivo periodontitis model with chemically induced tumorigenesis, chronic co-infection of P. gingivalis and F. nucleatum increased tumor size and invasion capacity via the IL-6/STAT3 axis." (PMID 38612423, 2024). "GroEL is an important virulence factor implicated in bacteria-host interaction and may be involved in the progression of periodontitis.P. gingivalis GroEL upregulates inflammatory cytokines (IL-6 and IL-8) in osteoblasts and PDLCs through NF-κB signaling and promotes alveolar bone loss in rats." (PMID 38596842, 2024). "In nine studies that included 574 controls and 1093 patients with PD, they discovered that IL-6-174G/C polymorphism is not linked to a risk of chronic periodontal disease, but this allele may raise the risk of aggressive periodontitis." (PMID 38396821, 2024). "Moreover, it has been reported that the administration of the ferroptosis inhibitor Fer-1 to mice with periodontitis reduces the expression of gingival IL-6, which is a proinflammatory cytokine that increases most prominently in gingival fibroblasts during periodontitis." (PMID 38670955, 2024). "Thus, IL-6 emerges as a pivotal cytokine connecting periodontitis and oral cancer." (PMID 38612423, 2024). "Indeed, when analyzing the severe periodontitis group, compared to the moderate periodontitis group, we observed a statistically significantly lower frequency of IL-6-producing monocytes and mDCs, as well as monocyte and mDC expression of IL-6 (after stimulus)." (PMID 39274511, 2024). "Proinflammatory substances like TNF-α, IL-6 and IL-1 aresecreted by activated microglia, which also use TLRs to initiate innate immune responses.Understanding the connection between glaucoma and periodontitis requires an understanding of inflammation and innate immunity." (PMID 39917226, 2024). "In addition, when P. gingivalis or its LPS, a keystone pathogen for periodontal dysbiosis and one of its most inflammogenic virulence factors, were added to the ligature during experimental periodontitis, they led to a further increase of IL-6 levels, Aβ deposition and memory function impairment." (PMID 39425138, 2024). "Moreover, an enhanced expression of IL-6 has been shown to stimulate the differentiation of osteoclasts and may therefore also contribute to bone resorption in periodontitis." (PMID 39258954, 2024). "Salivary and plasma levels of IL-1β, IL-6, and TNF-α increase with periodontal disease severity, and plasma MMP-8 and MMP-9 levels decrease after non-surgical periodontal treatment events, supporting the theory of periodontitis causing increased systemic inflammation." (PMID 38672972, 2024). "Our previous studies and our present study have shown that periodontitis-associated LPS and MetS-associated SFA, such as PA, synergistically stimulate ASMase, leading to increased production of ceramide in macrophages and subsequent upregulation of inflammatory cytokines such as IL-6 and IL-1b." (PMID 37176029, 2023).
periodontitis (continued). "In addition, IL-6 levels affected CRP levels in moderate–severe periodontitis patients with CAD." (PMID 37239434, 2023). "In addition, our ligature-induced model confirmed the distinguished bone resorption and the pro-inflammatory gene expression of IL-1β, TNF-α, CCL-2, Nos2, IL-17 and IL-6, which were highly enhanced during the progress of the early acute phase of new periodontitis." (PMID 38069063, 2023). "Of the studies included in this systematic review, four studies evaluated the levels of the pro-inflammatory cytokines IL-1β, IL-6, and TNF-α, the anti-inflammatory cytokine IL-10, and the matrix metalloproteinase-8 (MMP8), which is associated with the clinical manifestation of periodontitis." (PMID 37109642, 2023). "Overall, inflammation mediated by CRP/IL-6 may connect RC and periodontitis occurrence." (PMID 36824233, 2023). "The IL6 promoter gene was found to contain 19 CpG motifs where CpG motif methylation levels at −74 bp from canonical Transcription Start Site (TSS) were in the hypomethylated state in individuals with periodontitis and arthritis in comparison to healthy controls (p = 0.0001)." (PMID 36233348, 2022). "Il-1β (23.43% ± 8.01%) and IL-6 (30.43% ± 7.39%) positive cells were partially reduced in the positive area of the IL-1ra group compared to the periodontitis group of diabetic rats, but the proportion of positive cells was still much higher than that of the blank control and periodontitis groups." (PMID 36430410, 2022). "The periodontitis symptoms of mice in the F. nucleatum OMVs + ligation group were more serious than those of mice in the simple ligation group, with more osteoclasts and more inflammatory factors (IL-1β, IL-6, and TNF-α) being observed in their gingival tissues." (PMID 35391731, 2022). "Further experiments should then clarify whether the effects of periodontitis and/or orthodontic tooth movement on IL-6 and CXCL2 can be simulated in vitro and, if so, by what mechanism the effects of periodontitis and/or orthodontic tooth movement on these inflammatory mediators are realized." (PMID 34024010, 2022). "Since IL-6 and CXCL2 have pro-inflammatory and chemotactic activities that are increased in periodontitis, the first aim was to clarify whether IL-6 and CXCL2 are increased in gingival biopsies from periodontitis patients compared with periodontally healthy subjects." (PMID 34024010, 2022). "In an effort to explore possible downstream targets by which miR-146a may contribute to the pathobiology of disease, the levels of the main pro-inflammatory cytokines such as TNF-α, IL-1β, and IL-6 were studied in patients with chronic and aggressive periodontitis." (PMID 34645448, 2021). "Indeed, epidemiologic studies have shown that C‐reactive protein, which is synthesized in hepatocytes and activated by proinflammatory cytokines, including tumor necrosis factor alpha and IL‐6, is a modifying factor of periodontitis and nonalcoholic fatty liver disease." (PMID 34463983, 2021). "Early work on the influence of IL-6 in periodontitis suggested it might be protective." (PMID 35003055, 2021). "However, during periodontitis, the immune response is a double-edged sword because the cytokines and antimicrobial components produced during the immune response, such as IL-17, IL-6, IL-1β, TNF-α, ROS, and NETs, can induce bone resorption and soft tissue injury." (PMID 33777839, 2021). "Periodontitis‐related systemic inflammation may contribute to insulin resistance through elevated blood levels of adipocytokines, such as tumor necrosis factor alpha, IL‐6, and leptin, which inhibit the insulin receptor and its downstream signaling." (PMID 34463983, 2021). "This ability of the CPC-based mouthwashes to have anti-inflammatory action may have a beneficial impact, since it has been reported that IL-6 levels are higher in the diseased gingiva of patients with periodontitis than in the gingiva of periodontally healthy subjects." (PMID 33499560, 2020).